BTK (Bruton tyrosine kinase)
Diseases named in the same sentence as BTK in open-access papers (continued):
Sharing a sentence is not in itself a finding about the gene and the disease.
pneumonia (9 papers, 2018 to 2025). An acute, acute and chronic, or chronic inflammation focally or diffusely affecting the lung parenchyma, caused by an infection in one or both of the lungs (by bacteria, viruses, fungi, or mycoplasma.). "In our study, BTK inhibitor was an independent risk factor for the occurrence of pneumonia after COVD-19 infection." (PMID 39834945, 2024). "Patients receiving BTK inhibitors, those undergoing active therapy, and those without disease remission exhibited a higher risk for developing pneumonia." (PMID 39834945, 2024). "A pharmacovigilance study based on the FAERS database revealed that infection-related adverse reactions, such as pneumonia associated with ibrutinib and acalbrutinib, were among the most common safety signals linked to high mortality associated with these two BTK inhibitors." (PMID 39834945, 2024). "Importantly, infection-related adverse reactions, such as pneumonia and pleural effusion, were the most common risk signals related to high mortality associated with both BTK inhibitors, especially in elderly patients." (PMID 36438789, 2022). "A pharmacovigilance survey based on the FAERS database found that the most common, high mortality adverse reactions to BTK inhibitors (ibrutinib and acatinib) were infections, such as pneumonia and pleural effusions, especially in elderly patients." (PMID 36761953, 2023). "Patients treated with BTK inhibitors have high rates of infectious complications, including pneumonia, even with preserved CD‐4 cell counts." (PMID 37081733, 2023). "Among the top 20 PTs related to death reports, the terms infectious, pneumonia, pleural effusion, fall, asthenia, diarrhoea, and fatigue were all ranked high for these two BTK inhibitors." (PMID 36438789, 2022). "In patients with SARS‐CoV‐19 pneumonia under ibrutinib treatment (8/11), BTK inhibitor was maintained in 6 patients." (PMID 34558211, 2021). "Furthermore, an analysis of the Chinese subgroup in the Phoenix study revealed that, compared to the R-CHOP group, combining the BTK inhibitor ibrutinib with R-CHOP increased the incidence of pneumonia-related adverse reactions from 2.1% to 9.7%." (PMID 39834945, 2024). "Additionally, an analysis of the Chinese subgroup in the Phoenix study found that the incidence of pneumonia-related adverse reactions increased from 2.1% to 9.7% when comparing the BTK inhibitor ibrutinib combined with R-CHOP to the R-CHOP group." (PMID 39834945, 2024). "BTK inhibitors also increased common pneumonia by previous studies." (PMID 39834945, 2024). "A higher incidence of pneumonia was observed in patients who previously received anti-CD20 therapy (30.0% vs. 16.3%, P=0.048) and BTK inhibitor therapy (51.3% vs. 22.5%, P=0.001)." (PMID 39834945, 2024). "Higher incidence of pneumonia was observed in patients receiving anti-CD20 therapy (30.0% vs. 16.3%, P=0.048) and Bruton’s tyrosine kinase (BTK) inhibitor therapy (51.3% vs. 22.5%, P=0.001)." (PMID 39834945, 2024). "Of the adverse events of clinical interest for BTK inhibitors, infections were prevalent, with 50% of patients in the ZR-CHOP group experiencing various types of infections, including pneumonia (30%), upper respiratory tract infection (15%), and urinary tract infection (15%)." (PMID 40616640, 2025). "Second, to those with the DDON phenotype accompanying recurrent otitis media, sinusitis, or/and pneumonia, we recommend assessing their BTK expression level and investigating whether they belong to CGS involving the BTK and TIMM8A genes." (PMID 33013854, 2020).
acute lymphoblastic leukemia (8 papers, 2013 to 2025). Leukemia with an acute onset, characterized by the presence of lymphoblasts in the bone marrow and the peripheral blood. "ROR1 has been shown to crosstalk with the B‐cell receptor (BCR) through the BCR complex and Bruton's tyrosine kinase (BTK) as well as with associated signaling molecules in acute lymphoblastic leukemia (ALL) B cells." (PMID 35844694, 2021). "We used lysates from two different cell lines, a precursor-B acute lymphoblastic leukemia cell line with a somatic form of BTK, RCH-ACV43 (RRID: CVCL_1851), and the adrenocortical carcinoma cell line SW13 also with somatic BTK43 (RRID: CVCL_0542)." (PMID 40000607, 2025). "Downregulation of CD81 expression by aza/pano sensitizes acute lymphoblastic leukemia cells to chemotherapy and disrupts bruton tyrosine kinase (BTK) phosphorylation." (PMID 38389703, 2024). "Patients who develop acute lymphoblastic leukaemia (ALL) take BTK inhibitors." (PMID 34897650, 2022). "Kinase profiling revealed that GNF-7 not only evidently inhibited LYN, FYN, SRC, YES, BTK and CSK kinase that can also inhibited by dasatinib, but also inhibited ACK1 and mitogen-activated protein kinase (GCK) to kill NRAS-dependent cells in AML and acute lymphoblastic leukemia." (PMID 38037057, 2023). "To further examine whether synergy of ibrutinib with ethacridine is due to targets beyond BTK, we tested the drug combination in Jurkat D1.1 cells, a T-acute lymphoblastic leukemia cell line that does not express BTK." (PMID 26624983, 2016).
B cell deficiency (8 papers, 2015 to 2025). A broad classification of disorders where circulating numbers of B lymphocytes are decreased or ineffective. "For example, BTK deficiency is considered an advantage and B-cell deficiency was suggested to prevent inflammation, a major devastating sequela of the disease." (PMID 33519822, 2020). "CBA/CaHN-Btkxid/J mice with have a mutated version of the mouse BTK gene, are the mouse model of XLA in human, which exhibit a similar, yet around 50% milder B cells deficiency while XLA account for nearly 90%." (PMID 28915637, 2017).
graft versus host disease (8 papers, 2020 to 2024). An immune system disorder that occurs after allogeneic hematopoietic stem cell transplant and is a reaction of donor immune cells against host tissues. "Ibrutinib is an orally administered covalent Bruton’s tyrosine kinase (BTK) inhibitor that has been approved for a variety of B-cell malignancies and graft-versus-host disease by US Food and Drug Administration (FOOD&;Drug, 2017)." (PMID 33658926, 2020). "Similar to SYK inhibitors, BTK inhibitors are also being investigated in autoimmune diseases and some are approved for this purpose as for ITP, multiple sclerosis or graft-versus-host disease (GVHD)." (PMID 33363034, 2020). "Thirteen compounds targeting BTK in 9 indications having attained clinical trial status of phase 2 or beyond were found that encompass RA, SLE, MS, PV, SJ chronic spontaneous urticaria (CSU), idiopathic thrombocytopenia (ITP), graft versus host disease (GVHD) disease, and asthma indications." (PMID 34803999, 2021).
lymphoproliferative disorders (8 papers, 2019 to 2025). "Although type II cryoglobulinemia can also be caused by lymphoproliferative disorders, only two reported cases have suggested that BTK inhibitors were effective in type II cryoglobulinemia, both of which involved patients with a mutation in the MyD88 gene." (PMID 38765016, 2024). "We have previously observed that in MCL, another lymphoproliferative disorder characterized by a strong dependence on the microenvironment, the stabilization of β-catenin upon BCR stimulation is associated with BTK activity." (PMID 38139452, 2023). "A new treatment option for AIHA is targeting the B cell receptor signaling with drugs successfully used in chronic lymphocytic leukemia (CLL) and other lymphoproliferative disorders, such as Bruton tyrosine kinase (BTK) and phosphatidylinositol 3-kinase delta (PI3Kδ) inhibitors." (PMID 33466516, 2021). "Ibrutinib, a Bruton tyrosine kinase (BTK) inhibitor, has shown promise in treating EBV-related lymphoproliferative disorders, particularly in immunocompromised patients." (PMID 40733521, 2025).
Opportunistic infection (8 papers, 2020 to 2025). An infection that is caused by a pathogen that would generally not be able to cause an infection in a host with a normal immune system. "Beyond BTK blockade, ibrutinib also shows broad immunomodulatory effects that have been shown to be associated with infectious complications, including opportunistic infections." (PMID 38055081, 2023). "Inhibition of the innate immune system by BTK inhibitors has been associated with a small increase in opportunistic infections, particularly in the setting of combination chemotherapy or high dose corticosteroids and/or long-term use." (PMID 32503877, 2020). "Then inhibition of BTK has potential deleterious effects on immune responses, such as the development of opportunistic infections, including invasive fungal infections, in patients receiving Ibrutinib." (PMID 41398799, 2025). "This case highlights the importance of considering the possibility of opportunistic infections and the atypical presentation of such infections in immunocompromised patients, including those on BtK inhibitors." (PMID 41404449, 2025). "Beyond Bruton tyrosine kinase inhibition, Ibrutinib shows broad immunomodulatory effects that may promote the occurrence of infectious complications, including opportunistic infections." (PMID 38055081, 2023). "Both patients did not have drug side effects and opportunistic infections occurrence throughout the treatment, which suggested the safety of BTK inhibitors and other target therapy." (PMID 37644480, 2023).
Arrhythmia (7 papers, 2020 to 2025). Any cardiac rhythm other than the normal sinus rhythm. "Importantly, rilzabrutinib does not appear to be associated with the increased risk of infections, hepatic toxicity, or cardiac arrhythmias observed with other BTK inhibitors." (PMID 40222822, 2025). "Additional risk factors of QT prolongation, such as concomitant use of drugs that increase QT intervals, should be identified, as QT prolongation is one of the most common arrhythmias related to the use of BTK and PI3K inhibitors and nilotinib or bosutinib." (PMID 33322351, 2020). "The treatment exhibited a favorable safety profile, with predominantly grade 1 or 2 adverse events and no significant safety concerns commonly associated with BTK inhibitors, such as increased bleeding risk, hepatic toxicity, or cardiac arrhythmias." (PMID 40222822, 2025). "Pirtobrutinib induced a response in six of the eight patients with WM who were progressing on a covalent BTK inhibitor, without evidence of arrhythmia, a well‐known adverse event associated with covalent BTK inhibitors." (PMID 36051045, 2022). "The American Heart Association has also published a scientific statement on the prevention and management of arrhythmias and autonomic disorders in cardio-oncology (not specific to BTK inhibitors alone)." (PMID 38829647, 2024). "Importantly, rilzabrutinib did not exhibit safety concerns typically associated with Bruton's tyrosine kinase (BTK) inhibitors, including infections, liver toxicity, or cardiac arrhythmias." (PMID 40222822, 2025).
lymphoplasmacytic lymphoma (7 papers, 2018 to 2025). A clonal neoplasm of small B-lymphocytes, lymphoplasmacytoid cells, and plasma cells involving the bone marrow, lymph nodes, and the spleen. "Although drugs like methotrexate have traditionally been employed in treating lymphoplasmacytic lymphomas due to their cytotoxic properties and ability to cross the blood-brain barrier, recent support has emerged for ibrutinib, a Bruton tyrosine kinase inhibitor." (PMID 39165462, 2024).
melanoma (7 papers, 2019 to 2024). A malignant, usually aggressive tumor composed of atypical, neoplastic melanocytes. "Furthermore, we demonstrated that differential expression of all investigated Ibrutinib target genes (i.e., BTK, EGFR, ERBB2, ITK, JAK3, and TEC) is associated with apoptotic mechanisms in clinical melanoma samples." (PMID 38790974, 2024). "Upon further investigation, the bleeding was most probably caused by local invasion of the ciliary body melanoma into the vascularized iris, which both CLL and its treatment with BTK inhibitor ibrutinib could have accentuated." (PMID 35741122, 2022).
Thrombocytopenia (7 papers, 2021 to 2025). A reduction in the number of circulating thrombocytes. "TKIs targeting the VEGF receptor (VEGFR-TKIs) (i.e., sunitinib and regorafenib) and brutons tyrosine kinase (BTK) inhibitors (i.e., ibrutinib), increase bleeding risk through platelet dysfunction, thrombocytopenia, and interactions affecting coagulation pathways." (PMID 40952587, 2025). "For example, many of the BTK inhibitors currently in clinical trials are reporting dose-limiting toxicities of thrombocytopenia and neutropina in addition to dermatological toxicities, all of which are limiting their clinical uses." (PMID 41213918, 2025). "In addition, patients demonstrating grade 3 thrombocytopenia with bleeding or grade 4 thrombocytopenia should not receive BTK inhibitor treatment until resolution to baseline or grade 1, following which, BTKi treatment can be restarted at a reduced dose." (PMID 35159041, 2022).
Cerebral ischemia (6 papers, 2015 to 2025). Restriction of arterial blood supply to the brain associated with insufficient oxygenation to support the metabolic requirements of the tissue. "The expression of BTK and pBTK is upregulated in microglia under conditions of cerebral ischemia and oxygen–glucose deprivation (OGD)." (PMID 40263985, 2025). "To investigate changes in BTK expression following cerebral ischemia, we utilized C57BL/6 male mice to establish an MCAO model." (PMID 40263985, 2025). "Bruton’s tyrosine kinase (BTK) is a class of tyrosine kinases involved in the activation of the NLRP3 inflammatory complex in brain ischemia and reperfusion, resulting in the expression of mature caspase-1, as well as increased levels of IL-1." (PMID 36552584, 2022). "Ito and colleagues showed that ibrutinib, a potent BTK inhibitor, inhibits NLRP3 inflammasome signaling in a focal brain ischemia-reperfusion model." (PMID 35008558, 2021). "BTK is a tyrosine kinase that participates in the activation of the NLRP3 inflammasome, which in turn leads to the activation of caspase-1 and the production of mature IL-1β in the process of cerebral ischemia." (PMID 35008558, 2021).
colorectal cancer (6 papers, 2016 to 2024). A primary or metastatic malignant neoplasm that affects the colon or rectum. "The discovery of a novel oncogenic isoform of BTK abundantly expressed in breast, ovarian, prostate and colorectal cancer has been another essential factor indicating the potential efficacy of BTK in the management of solid tumors." (PMID 35456016, 2022). "We evaluated the expression of a novel BTK isoform, p65BTK, in colorectal cancer (CRC), to identify its impact on survival." (PMID 31238520, 2019). "Notably, the kinase domain is conserved and therefore inhibited by the available BTK-targeting drugs (Ibrutinib, Spebrutinib, etc.)which we used to demonstrate that p65BTK is an actionable target in drug-resistant colorectal carcinomas." (PMID 34164404, 2021).
ischemic stroke (6 papers, 2015 to 2025). A stroke disorder caused by obstruction of blood flow to the brain, due to thrombotic (local blood clot formation) or embolic (due to a blood clot or other material traveling from another site) event. "Although previous studies have confirmed significant BTK expression in microglia, the potential of Evobrutinib to treat ischemic stroke by modulating microglial function and its underlying mechanisms remain to be elucidated." (PMID 40263985, 2025). "In this study, we explored the efficacy of Evobrutinib, a third-generation BTK inhibitor, in an animal model for ischemic stroke treatment for the first time." (PMID 40263985, 2025). "Previous preclinical work in ischaemic stroke has found that the BTK inhibitor ibrutinib inhibits IL-1β maturation and NLRP3 inflammasome activation in infiltrating macrophages and neutrophils in the infarct area of the MCAO model." (PMID 30758770, 2019). "Moreover, inhibiting Bruton’s tyrosine kinase (BTK), an upstream activator of the NLRP3 inflammasome, can reduce the infarct volume and associated neurological damage following ischemic stroke." (PMID 40075143, 2025). "Besides, studies indicated that inhibiting BTK could be a potent therapeutic target in ischemic stroke, and modulation of signaling via BTK prevented T cell-mediated autoimmune diabetes." (PMID 34605340, 2021). "Our study indicates that BTK is essential for NLRP3 inflammasome activation and could be a potent therapeutic target in ischaemic stroke." (PMID 26059659, 2015).
lung adenocarcinoma (6 papers, 2020 to 2025). A carcinoma that arises from the lung and is characterized by the presence of malignant glandular epithelial cells. "A recent study in which >500 lung adenocarcinoma cases were analyzed for possible contribution of BTK to an immune-dominant profile of the TME revealed that BTK expression in the TME was associated with a less aggressive disease and an improved survival outcome." (PMID 33937249, 2021). "Altogether, the results presented here indicate that KLRG1, BTK, CCR2 and SCML4 play important roles in the development of lung adenocarcinoma, and their expression can be effective biomarkers to predict LUAD patients’ survival." (PMID 34187403, 2021). "The expression of LDHA, CDKN3, and SHC1 were significantly raised in lung adenocarcinoma compared to non-cancer cells, whereas BTK expression was higher in non-cancer than in cancer cells (Figures 8A2, B2, C2, D2)." (PMID 40182622, 2025). "Considering the relationship between the risk model and the presence of immune infiltration, and immunotherapy, we further explored the possible roles of the two genes used to construct the model: BTK and DPEP2 genes in the tumor microenvironment of lung adenocarcinoma." (PMID 36991102, 2023). "In this study, through the analysis of the database and clinical samples, we found four markers (KLRG1, BTK, CCR2 and SCML4) which may play important roles in the development of lung adenocarcinoma." (PMID 34187403, 2021). "In a word, our research shows that the expressions of key genes of sphingolipid metabolism, such as LDHA, CDKN3, SHC1 and BTK, are obviously different from those of non-cancerous tissues in lung adenocarcinoma, and can obviously affect the prognosis of LUAD patients." (PMID 40182622, 2025).
Ventricular arrhythmia (6 papers, 2019 to 2025). "While BTK inhibition has been associated with atrial arrhythmias, there are conflicting clinical data showing QT prolongation or increased risk for ventricular arrhythmias with BTK inhibitors." (PMID 36902065, 2023). "Further studies elucidating the electrophysiological mechanism of BTK inhibition in the setting of RV dysfunction and ventricular arrhythmias are needed." (PMID 36902065, 2023). "Ibrutinib, a tyrosine kinase inhibitor (TKI), is associated with a higher incidence of atrial and ventricular arrhythmias compared to non-Bruton tyrosine kinase (BTK) TKIs and non-TKI therapies in patients with hematologic malignancies." (PMID 39238728, 2024).